IL2 (interleukin 2)
Diseases named in the same sentence as IL2 in open-access papers (continued):
Sharing a sentence is not in itself a finding about the gene and the disease.
tumor (continued). "More importantly, we reveal a relevant mechanism that PIK3CD, but not PIK3CA and PIK3CB, is transcriptionally regulated by the pro‐inflammatory IL2/JAK3/STAT5 axis and tumor‐infiltrating immune cells such as lymphocytes." (PMID 38545256, 2024). "Both SIA‐CIgG CAR‐T cells and HER2 CAR‐T cells secreted more IL‐2, IL‐5, TNF‐α, IFN‐γ, and IL‐13 compared to non‐transduced T cells when eliminating tumor cells." (PMID 39178136, 2024). "With tumor cell stimulation, the CART-19 cells exhibited heightened functional cytokine and chemokine secretion, especially the production of GM-CSF, IFN-γ, IL-2, IL-4, IL-8, IL-12, IL-13, MIP-1α/β, and TNF-α/β." (PMID 38773607, 2024). "Among them, angiogenesis, IL6-JAK-STAT3, IL2/STAT5, complement system, interferon gamma response, and G2M checkpoint, are crucial for tumour growth, inflammation, and immune system evasion." (PMID 39107713, 2024). "For instance, CAR-T cells engineered with IL-7 and CCR2b (7x2b CAR-T) showed improved survival and migration to the tumour site by boosting IFN-γ, IL-2, and granzyme production." (PMID 39450176, 2024). "Cytokines play a crucial role as mediators in the TME, with cytokines involved in adaptive immune responses (e.g., IFNγ, IL-2, IL-12, and TNF) positively impacting anti-tumor immunity." (PMID 38928150, 2024). "In the IRF1 knockdown group, IL-2 treatment simulated the effect of IRF1 and significantly inhibited the tumor growth." (PMID 38915471, 2024). "This interaction inhibits T-cell activation or induces apoptosis, resulting in reduced secretion of anti-tumor cytokines, such as IFN-γ and IL-2." (PMID 39781272, 2024). "The GSEA results also indicate that ESCO2 is involved in cancer inflammation control, including IL2 STAT5 signaling, which raises the possibility that ESCO2 also controls the tumor immune microenvironment." (PMID 38605349, 2024). "Engineered T cells targeting LMP1 in EBV-positive NPC cells have also demonstrated increased IFN-γ and IL-2 production, effectively killing LMP1-overexpressing NPC cells in vitro and reducing tumour growth in vivo." (PMID 39450176, 2024). "Two prospective phase II trials showed that the DC-CIK can induce the proliferation of autologous tumor-specific T cells and the expression of IFN-γ, IL-2, and TNF-α in CD4+ T cells." (PMID 38476223, 2024). "T helper (Th) cells play a crucial role in enhancing anti-tumor and anti-inflammatory immune responses by releasing various cytokines such as TNF-α, Granulocyte-Macrophage Colony-Stimulating Factor (GM-CSF), IL-2, IL-6, IL-10, IL-21, and others." (PMID 38755133, 2024). "LILRB4 blockade restored IL-2 production in HDVax-induced cells and enhanced their expression of IFNγ/TNF and CD40L in both T3 and F244 tumour models." (PMID 39048822, 2024). "Our results revealed that when LIPUS irradiated normal mouse for 14 and/or 21 days, even at day 30 after inoculation with 4 T-1 tumors, LIPUS promoted the release of some critical cytokines such as IL-2, IL-7 and IFN-γ in the plasma of tumor-bearing mice." (PMID 38349555, 2024). "Upon antigen stimulation, CD8+ T cells can rapidly differentiate into effector cells and produce a multitude of effector cytokines (e.g., IL-2, TNF-α, and IFN-γ) and granzyme B to effectively eliminate tumor cells." (PMID 39519411, 2024). "Tumor models of miR-21 knock-in mice treated with anti-PD-L1 antibody and radiation resulted in increased T-cell, IFN-γ, IL-2, and reduced tumor size coupled to a decreased PD-L1 expression, thus improving immunotherapy via T-cell immune response activation." (PMID 38963803, 2024). "Th1 cells are differentiated under the direction of IL-12 and mainly secrete interleukin-2 (IL-2), interferon-γ (IFN-γ), and tumour necrosis factor-β (TNF-β) to inhibit tumour cell growth and promote the cellular immune response." (PMID 38475858, 2024).
tumor (continued). "In a study of CAR-T cell therapy combined with infusing aAPC, aAPC infusion promoted the specific recognition of CAR-T cells to tumor cells and released more IFN-γ, TNF-α, and IL-2." (PMID 39372416, 2024). "This synthetic IL‐2 pathway induces potent TCR‐T or CAR‐T cell infiltration and effective tumor regression in immune‐excluded solid tumor models while avoiding associated systemic or off‐target toxicities." (PMID 39422665, 2024). "Preclinical studies have shown that the allogeneic tumor cell line RCC-26 exhibits natural immunogenic potential, which is enhanced by the expression of CD80 costimulatory molecules and IL-2 secretion." (PMID 39575257, 2024). "Mice were treated with IL-2 in combination with agonistic antibodies to CD40, a combination that was previously demonstrated to result in marked synergistic anti-tumor effects, to determine how the thymus was effected during and after administration." (PMID 39315105, 2024). "Compared with conventional anti-MSLN CAR-T cells, CAR-T cells coexpressing CCR2b exhibited increased CCL2-induced calcium flux and transport, increased levels of IL-2, IFN-γ, and TNF-α, and enhanced cytotoxicity against MSLN+ tumor cells in vitro." (PMID 39023820, 2024). "In contrast, Tet2 overexpression in combination with IL-2 stimulation led to more increase in Cgas expression than either alone, suggesting that TET2 synergizes with STAT5A signaling to promote tumor cGAS expression." (PMID 38177099, 2024). "TPV/eGFP-treated subjects demonstrated a marginal regression in tumor volume compared to vehicle controls, again supporting the role CCL-2 and IL-2 play in the negative regulation of BxPC-3 human PDAC xenografts in our immunocompromised test system." (PMID 39200298, 2024). "Upon recognition of tumor antigens, CD8+ T cells are activated and IL-2 can enhance the antitumor immune response mediated by CD8+ T cells." (PMID 38923962, 2024). "We then examined the extent of T-cell infiltration and activation in the OVA vaccine (containing OVA peptide, imiquimod and IL-2) and CD3xTRP1 double therapy, as well as its impact on innate immune cells in both B16F10 and KPC3-TRP1 tumor models." (PMID 38167722, 2024). "This imbalance affects tumor progression and invasive behaviors such as tumor metastasis, and the TGF-β/IL-2 and IL-6 cytokine axes greatly contribute to Th17/Treg homeostasis." (PMID 39534095, 2024). "Tumor-derived PGE2 also restricts the proliferation and effector differentiation of TCF1+ stem-like CD8+ T cells by suppressing the IL-2 signaling pathway." (PMID 39402302, 2024). "ELISA reveals that XLLXF combined with trastuzumab increases the levels of IL-15, IL-2, TNF-α, and IFN-γ in tumor-bearing mice." (PMID 38379418, 2024). "Necrotic cell death was observed in post-treatment tumor tissues, accompanied by increased secretion of IFN-γ and IL-2." (PMID 38515576, 2024). "Although nanobody-based CAR-T cells and 376.96 scFv-based CAR-T cells have comparable cytotoxicity against IMR5 tumor cells, a significantly higher level of cytokines (IFN-γ, IL-2, and TNF-α) was released from B12(VHH)-CAR-T cells compared to others." (PMID 37739951, 2023). "Specifically, we observed an increase in the levels of immunostimulatory cytokines IL-2 and IFN-γ, as well as the recruitment of NK cells and M1 macrophages to the tumor site." (PMID 37395796, 2023). "TNF-α and IFN-γ expression levels remained unchanged and were comparable to control levels on the fourth and seventh days, but IL-2 levels increased greatly on the seventh day after Ce6-PDT therapy, mimicking the pattern as seen in the tumor." (PMID 36835310, 2023). "In recent years, some cytokines, including IL2, IL12, IL15, IL21, GM-CSF, and interferon-α, have been found to regulate the composition of tumor microenvironment and modulate the efficacy of immune therapy in murine cancer models." (PMID 36959575, 2023).
tumor (continued). "Tregs isolated from the tumor infiltrate are specific for E6 and E7 of HPV16 in cervical cancer and inhibit the secretion of cytokines such as IFN-γ and IL-2 produced by antitumor T cells." (PMID 37631922, 2023). "In brief, tumor surgical specimens were minced into fragments, and TIL was cultured in a previous rapid expansion phase (preREP) with high dose IL‐2, followed by amplification to a large number in a rapid expansion phase (REP)." (PMID 36028997, 2023). "In tumor microenvironments, loaded chemotherapeutic paclitaxel (PTX) and immunotherapeutic interleukin-2 (IL-2) were rapidly released in response to acidic pH." (PMID 36986636, 2023). "From these pieces of tissue, we generated prostate infiltrating lymphocytes (PILs) from TURP bulk specimen by in vitro culture with IL-2 (pre-REP) or using a rapid expansion protocol (REP) after pre-REP, as classically performed from tumor fragments." (PMID 37370724, 2023). "On the 24th hour and on the 9th day after, tumour induction blood was collected to estimate levels of VEGF, NO, TIMP-1 and IL-2 (interleukin-2)." (PMID 38067491, 2023). "Here, using two mouse tumor models, we demonstrate that adding long-acting CD122-directed IL-2 complexes (IL-2c) to RT/anti-PD1 further increases tumor-specific CD8+ T cell numbers." (PMID 37045833, 2023). "Due to a simultaneous stimulation by IL-2 and TGF-β, and the expression of the high affinity IL-2 receptor, T cells are more likely to differentiate into CD4+ Treg cells that protect the tumor by consuming IL-2 and secreting IL-10 and TGF-β." (PMID 37238744, 2023). "A fusion protein of IL-2 to L19, a monoclonal antibody targeted to an angiogenesis marker, L19IL2, enables preferential delivery and activation of the cytokine within the tumor cells." (PMID 36900196, 2023). "Similar to the lower signaling mediated by intrinsically generated IL-2, short-term culture with exogenous IL-2 promoted the CD62L+CCR7+ memory CAR-T cells possessing stronger propagating ability and better tumor control in vivo." (PMID 38049832, 2023). "IL-2 can activate multiple signaling pathways, including the JAK-STAT, PI3K-AKT, and MAPK pathways, exerting pro- and anti-tumor effects." (PMID 37516849, 2023). "By anchoring IL-2 and anti-CD137 to the surface of liposomes, these immunostimulants can be ensured to primarily act at the tumor site, thus reducing systemic toxicity." (PMID 37808190, 2023). "In the case of HeLa cells, they produce proinflammatory cytokines such as TNF-α, IL-6, IL-2, IL-12, and IFN-γ to sustain tumor development and proliferation over the long term." (PMID 37767520, 2023). "They release a variety of cytokines such as IL-2, INF-γ, and TNF-β to participate in anti-tumour effects directly." (PMID 37767473, 2023). "IL-6/STAT3 as well as the IL-2/STAT5 pathway activates downstream target genes to protect tumour cells from apoptosis, increase tumour cell proliferation, cell cycle progression, invasion, and metastasis, and are involved in drug resistance." (PMID 36980202, 2023). "DCs take up tumor antigens and migrate to lymph nodes to activate the IL-2-producing CD4+ (Th1) and tumor-specific CD8+ (Th2) T cells, which migrate to the tumor site and eradicate the viable antigen-positive tumor cells." (PMID 36839774, 2023). "Together, our data suggest that combined IL12-MSA and IL2-MSA promotes the activation and differentiation of SIY-reactive CD8+ T cells across multiple tissue sites, while restraining Tregs in tumor-bearing lungs." (PMID 37669107, 2023). "As a result of this mechanism, pro-apoptotic cytokines including IL-2, IL-12, and TNF phagocytose the targeted tumor cells, leading to cell death." (PMID 37190310, 2023). "Upregulation of CD39 was accompanied by the expression of inhibitory receptors and reduced IL-2 and TNF secretion, and tumor growth, indicating CTLs’ exhaustion." (PMID 37835465, 2023).
tumor (continued). "RMS-high group was related to worse prognosis, which was partly attributed to significant activation of EMT, Notch, IL-2/STAT5, IL-6/JAK/STAT3, angiogenesis signaling pathways, which was instrumental in tumor invasion." (PMID 37124622, 2023). "Exhausted cytotoxic T cells are unable to lyse tumor cells, they have impaired effector functions and they show an inability to product pro-inflammatory cytokines (e.g., TNF-alpha, IFN-gamma, IL-2)." (PMID 37427115, 2023). "EBV-positive T-cells were only established from nasal T/NK lymphoma patients using IL-2-supplemented medium, whereas all other reports of EBV-positive lymphocytes isolated from tumor tissue mention populations expressing B-cell maker CD20." (PMID 36639629, 2023). "IL-2 can promote activation and proliferation of CD8+ T cells in early tumor stage but can deplete CD8+ T cells in late tumor stage." (PMID 36835413, 2023). "With this regard, by reducing IL-2 signal strength, CD8(+) T cells can be successfully cultivated in vitro to acquire stemness and mediate persistent tumor suppression in CAR-T therapy." (PMID 38049832, 2023). "Regulatory T cells CD4+CD25+CD3+ are abundant in the tumor mass and the malignant ascites of OC patients with later stage disease, and they suppress the production of IFN-γ and IL2 and subsequent T cell activation." (PMID 37445860, 2023). "Many cycles of patient-derived type I CD4+ T helper cells (Th1) provided by IP together with the cytokines IL-2 and IFN were shown to improve the anti-tumor activity of autologous CD8+ T cells against the tumor-specific glycoform of MUC1." (PMID 37190310, 2023). "The therapeutic effectiveness of the B16-F10 melanoma tumor was improved by a thermo-sensitive nano-hydrogel co-loaded with DOX, IL-2, and IFN-γ, which boosted tumor cell death and enhanced replication of CD3+/CD4+ and CD3+/CD8+ T cells." (PMID 37102943, 2023). "In parallel, we investigated the secretion of IL-2 and IFN-γ, two key cytokines for anti-tumor immunity." (PMID 38116319, 2023). "Genetic deletion and pharmacologic inhibition of NLRP3 enabled the development of Th1 immunity, increased intratumoral levels of IL2, CD8+ T cell–mediated tumor suppression, and ultimately limited tumor growth." (PMID 37772994, 2023). "IL-2, IFN-γ, and TNF-α are key cytokines that play pivotal roles in the immune response to cancer by activating various immune cells and promoting tumor cell apoptosis." (PMID 37958581, 2023). "The expressions of cytokines, IFNγ, granzyme B (GZMB), and IL-2 in the sorted T cells are attenuated in the CAP-treated mice, indicating that the functions and activities of tumor-infiltrating T cells are impaired by CAP treatment." (PMID 37189453, 2023). "Initially, the tumor grew rapidly on Dog 3, but a transient decrease in tumor size (PR) was observed after the third CAR-TIL injection and first IL-2 injections." (PMID 36765608, 2023). "After a literature review, we collect factors that directly regulate the function of NK cells, and the gene list is IL2, IL15, IL18, IL21, all of which promote NK cell-mediated tumor death, while IL6, TGFβ and TNFα promote NK cell exhaustion." (PMID 38159250, 2023). "Critical to regulating anti-tumor immune responses within the TME are immune cells, such as DCs and MDSCs, which are influenced by IL-2 /IL-2R signaling." (PMID 37516849, 2023). "Surface-expressed GRP78 was discovered to boost the generation of diverse cytokines with anti-tumor properties, including interferon (IFN)-γ, interleukin (IL)-2, tumor necrosis factor α (TNFα), and granulocyte–macrophage colony-stimulating factor (GM-CSF)." (PMID 37605113, 2023). "A combined treatment of IL-2/JES6 immunocomplexes and chemotherapy hampers the tumor growth and induces KILR CD8+ T cells." (PMID 36705564, 2023). "In vitro incubation of inactive lymphoid cells with recombinant IL-2 results in the production of lymphokine-activated killer (LAK) cells, which are cells that are capable to lyse tumor cells." (PMID 37345057, 2023).
tumor (continued). "The combination of LIGHT and interleukin-2 increased CTLs in mice with COAD achieved a long-lasting, anti-tumor ability." (PMID 37511932, 2023). "In this regard, a significant increase in lymphocyte-activating IL2 was observed along with inflammasome-related IL1β and IL18, which play dual roles in cancer progression and anti-tumor immune responses." (PMID 36831596, 2023). "MSCs are able to deliver a variety of cytokines and growth factors to the tumor site that were identified as anti-tumor agents, comprising IFN-α, IFN-β, IFN-γ, IL-2, IL-7, IL-12, IL-15, IL-18, IL-25, and NK4, an antagonist of HGF." (PMID 37686315, 2023). "In recent years, many cytokines, such as IL-2, IL-15, IL-21, GM-CSF, and IFN-α, have proven effective in preclinical tumor models and are used as potential options for cancer immunotherapy." (PMID 37275909, 2023). "Here, we studied T cell responses to IL12-MSA alone or in combination with IL2-MSA in mice with KP lung tumors to better understand cytokine-mediated T cell activation and tumor control of ICB-resistant NSCLC." (PMID 37669107, 2023). "On their arrival to the tumor site NK cells get activated by soluble (e.g. IL-2, IL-15, TNF-α, and IFN-γ) and contact-dependent signals from the tumor microenvironment (TME)." (PMID 37841273, 2023). "The cytotoxic ability of IL-36γ–treated neutrophils was enhanced by cytokines, such as IL-1β, IL-2, or TLR ligands, such as LPS or irradiated tumor cells." (PMID 37317970, 2023). "Functionally, neoadjuvant chemotherapy induces proinflammatory cytokines and decreases pro-tumor cytokines from tumor-infiltrating T cells, with enhanced TNF-α and IL-2 and reduced IL-4 and IL-10 expression." (PMID 37173915, 2023). "As well, tumor cells secrete immunosuppressive cytokines such as transforming growth factor-β (TGF-β) and interleukin-2 (IL-2) which promote the generation of Treg cells instead of effector T cells." (PMID 38275827, 2023). "Z. multiflora essential oil (500 mg/kg) reduced tumour weight and balanced T helper 1 levels by increasing the secretion of TNF‐α, Interferon‐gamma (IFN‐γ) and IL‐2 and decreasing IL‐4 levels." (PMID 37697969, 2023). "In co-cultures with CD1d+ tumor cell lines, the CD1d-Vδ2 bsTCE triggered type 1 NKT cells to secrete Th1 and Th2-type cytokines, including IL-2, IL-4, tumor necrosis factor (TNF), and interferon (IFN)-γ, whereas Vγ9Vδ2-T cells mainly secreted TNF and IFN-γ." (PMID 36868236, 2023). "The presence of IL2 in tumor tissues promoted the proliferation of the CD8+ T and NK cells to suppress tumor growth, resulting in a 68% tumor inhibitory rate in a subcutaneous 4T1 tumor-bearing mouse model." (PMID 38067480, 2023). "For example, interleukin-2 (IL-2) is an important immunomodulatory cytokine, mainly produced by CD4-positive (CD4+) T cells, and thus can be utilized to target some tumor cells that overexpress interleukin-2 receptor (IL-2R)." (PMID 37508840, 2023). "Before 2007, treatments were based on the immunosuppressive agents interleukin-2 (IL-2) and interferon-alpha (INF-α); the latter inhibits tumour proliferation and stimulates mixed histocompatibility complex expression." (PMID 36831392, 2023). "Th1 cells secrete cytokines (IL-2, TNF-α, and IFN-γ) that stimulate M1 macrophages, NK cells, and CD8+ T cells to increase the respective anti-tumor activities and prolong cell survival." (PMID 38140230, 2023). "GM-CSF cytokines have been found to be more effective than other researched cytokines, such as IL-2, IL-4, IL-5, and y-IFN, as it activates a tumor-specific T cell response and is used in the production of GM-CSF-secreting whole-cell cancer vaccines." (PMID 37681891, 2023).